FOXO1 (forkhead box O1)
Diseases named in the same sentence as FOXO1 in open-access papers (continued):
Sharing a sentence is not in itself a finding about the gene and the disease.
breast carcinoma (continued). "Further, on correlating our results we found a strong correlation of FOXO1 mRNA expression with the age of the patient (p = 0.008), age at first live birth (p = 0.0003), tumor size (p = 0.05), and lymph node status (p = 0.01) of the breast cancer patients." (PMID 35309123, 2022). "FOXO1 mRNA expression was found to be downregulated in 69.29% cases (88/127) and out of which 73.80% cases (65/88) were categorized under histological grade I and II of breast cancer." (PMID 35309123, 2022). "Therefore, for better understanding the role of FOXO1 in breast cancer, in our study we examined the FOXO1 mRNA and protein expression in Breast cancer samples of Indian breast cancer patients." (PMID 35309123, 2022). "FOXO1 mRNA downregulation was earlier reported to show a significant association with the lymph node status and age of the patients in prostate cancer cases, our study also reveals this strong correlation of FOXO1 mRNA expression with these clinical parameters in case of breast cancer patients." (PMID 35309123, 2022). "Our previous study indicated that tanshinones could reduce the expression of the FOXO1 transcription factor in human breast cancer Bcap37 cells." (PMID 35744840, 2022). "Correlation study of FOXO1 mRNA expression levels with clinical parameters of Breast Cancer case." (PMID 35309123, 2022). "We, therefore, next examined whether FOXO1 regulated breast cancer stemness through modulating the expression of IL6 and ALHD1." (PMID 35637961, 2022). "Thus, understanding the regulation of FOXO1 expression is vital in managing and monitoring the cancer in general and breast cancer in particular." (PMID 36539739, 2022). "Interestingly, from a clinical perspective, stratifying patients based on either the expression levels of NTRK2 (TRKB) or FOXO1 is predictive of a good prognosis (overall survival) in breast cancer, similar to prognosis based on PR expression." (PMID 36034422, 2022). "DNMT3B is known to influence breast cancer development via regulation of the STAT1/FOXO1 pathway." (PMID 36061358, 2022). "Correlation of FOXO1 Protein Expression level with clinical parameters of Breast Cancer Patients." (PMID 35309123, 2022). "For example, the expression of FOXO1 predicted disease-free survival in breast cancer." (PMID 34035814, 2021). "Moreover, miR-96 is known as a tumor suppressor in pancreatic cancer by suppressing KRAS, as well as in endometrial and breast cancers by suppressing FoxO1 and FOXO3 genes." (PMID 33788050, 2021). "In addition, FOXO1 activation supports metastases in breast cancer cells through the upregulation of MMP-1." (PMID 32629884, 2020). "FOXO1 can act as a tumor suppressor in several cancers, including breast cancer." (PMID 32708561, 2020). "It has been reported that FOXO1 can act as a transcription factor for ERα in breast cancer, which may contribute to positive feedback formation." (PMID 33098638, 2020). "Knock down of FoxO1 inhibited tamoxifen sensitivity in breast cancer cells." (PMID 31767027, 2019). "Also, RA has been shown to increase FOXO1 expression, in a time-dependent manner, in human breast cancer." (PMID 30978209, 2019). "In addition, it was reported that matrix metalloproteinase-1 (MMP-1) is induced by FOXO1 and enhances the invasive potential of human breast cancer cells." (PMID 31823759, 2019). "Consistently, decreased FoxO1 levels were observed in breast cancer tamoxifen-resistant cells." (PMID 30646603, 2019). "However, it is unclear that TIMP3 inhibits the progress of breast cancer via the FOXO1/STAT1 pathway." (PMID 29796115, 2018). "Upregulated DNMT3B is critical for promoter methylation and decreased expression of TIMP3, which could promote progression of breast cancer via the TIMP3/STAT1/FOXO1 pathway." (PMID 29796115, 2018). "Finally, our results showed that miR-29c exerted its function in breast cancers by regulating the TIMP3/STAT1/FOXO1 pathway." (PMID 29796115, 2018).
breast carcinoma (continued). "Down-regulation of FOXO1 by microRNAs in breast cancer cell lines may result in the transformation and maintenance of an oncogenic state of breast cells." (PMID 29324832, 2018). "This hypothesis is supported by the work of Guttilla and White (2009) showing that FOXO1 mRNA is down-regulated in breast cancers compared to normal breast tissue, and that overexpression of FOXO1 induces MCF-7 cell death." (PMID 29484124, 2018). "For instance, FOXO1 3′UTR exerts an inhibitory effect on the metastases of breast cancer cells." (PMID 28186968, 2017). "In human breast cancers higher expression of AMPKα and FOXO1 extended survival." (PMID 26919657, 2016). "FOXO1 is an important transcription factor downstream of the PI3K-Akt signaling pathway and has been implicated as a tumor suppressor in several cancers, including mesothelioma, Ewing’s sarcoma, gastric cancer, oral cancer, prostate cancer and breast cancer." (PMID 25739100, 2015). "Treatment with 5-FU was previously reported to enhance FOXO-1 levels in breast cancer cells." (PMID 26472352, 2015). "This suggests that modulating FOXO1 expression may serve as a novel strategy to sensitize breast cancers to chemotherapy and/or radiotherapy." (PMID 23946796, 2013). "It seems that targeting of FOXO1 by microRNAs may contribute to transformation or maintenance of an oncogenic state in breast cancer cells." (PMID 20815877, 2010). "Therefore, we hypothesized that adipocytes might accelerate the progression of breast cancer by modulating FOXO1/miR-135b/circCNIH4 axis through EMT pathway." (PMID 39135158, 2024). "Besides, we also found that FOXO1 and circCNIH4 might have the potential as prognostic biomarkers for breast cancer patients due to the abilities to suppress the EMT pathway." (PMID 39135158, 2024). "FOXO1 participated in modulating of many biological processes, such as apoptosis, DNA damage repair, cell cycle arrest and/or oxidative stress resistance, and decreased FOXO1 mRNA levels were detected in breast carcinoma, prostate cancer, osteosarcoma, hepatocellular carcinoma and Ewing sarcoma." (PMID 32902145, 2020). "The nuclear export of FOXO1 by elevated pAkt and leading to loss of control MALAT1 at its promoter might be a mechanism for MALAT1 mediated resistance and cell invasion in HER2+ breast cancer cells." (PMID 32708561, 2020). "Therefore, induction of BIM by FOXO1 may be a key step in maintaining the BIM level in breast cancer cells and dictating their response to chemotherapy drugs." (PMID 31827405, 2019). "In addition, the transcription of NAMPT gene can be directly regulated by FOXO1 in breast cancer." (PMID 31448236, 2019). "Furthermore, we suggest the targeting of AMPK and FOXO1 to combat breast cancer." (PMID 26919657, 2016). "Additionally, the increased tumorigenicity observed in response to AGK-mediated downregulation of FOXO1 in breast cancer may be due to aberrant activation of AKT, which is a major downstream effector of the EGFR." (PMID 26443540, 2016). "Furthermore, three microRNAs, miR-27a, miR-96, and miR-182, have all been found to directly target FOXO1 and regulate endogenous FOXO1 protein expression in breast cancer cells, while suppression of these microRNAs resulted in an increase in FOXO1 protein and a decrease in cell growth." (PMID 25472505, 2014). "Furthermore, overexpression of AGK enhanced G1-S phase transition in breast cancer cells, which was associated with activation of AKT, suppression of FOXO1 transactivity, downregulation of cyclin-dependent kinase inhibitors p21Cip1 and p27Kip1 and upregulation of the cell cycle regulator cyclin D1." (PMID 24886245, 2014).
breast carcinoma (continued). "FOXO1 and FOXO3a are among the most studied FOXO transcription factors and have been shown to have significant roles in breast cancer progression and regulation." (PMID 40244097, 2025). "Glioblastoma multiforme (Glioblastoma multiforme, GBM) and basal‐like breast cancer (basal‐like breast cancer, BBC) exhibit FOXO1‐driven characteristics." (PMID 41002121, 2025). "Mechanistically, exogenous FGF21 treatment enhanced the anti-apoptotic ability of breast cancer cells through STAT3 and Akt/FoXO1 signaling pathways, and mitigated doxorubicin-induced cell death." (PMID 38238320, 2024). "Our results show that FOXO1 binds to the CYP1B1-AS1 promoter sequence and positively regulates its expression in breast cancer cells." (PMID 37640964, 2023). "Mechanistically, TRIB3 can facilitate breast cancer stem cells through regulating AKT to interfere with the FOXO1-AKT interaction and inhibit FOXO1 phosphorylation, ubiquitination, and degradation by E3 ligases SKP2 and NEDD4L." (PMID 37732314, 2023). "The C-terminus of forkhead box O1 (FOXO1) is downregulated by NEDD4L via ubiquitination at K463 site, which inhibits breast cancer stem cells." (PMID 38027016, 2023). "The depletion of PI3K and activation of FOXO1 has led to cell cycle arrest and apoptosis in MCF-7 breast cancer cells." (PMID 38202644, 2023). "ZNF750 was recently described as an EMT repressor in breast cancer, an activity shared by OVOL2, TP63, and FOXO1." (PMID 38066300, 2023). "Contrarily, the tumor suppressor and transcription factor Foxo1 binds to the NAMPT gene’s 5' flanking region and reduces the expression of NAMPT in breast cancer cells, an action that is counteracted by the insulin-PI3K-AKT signaling pathway." (PMID 36160449, 2022). "SOX2 can inactivate FOXO1 in embryonic stem cells, while FOXO1 can inhibit SOX2 transcription in breast cancer cells." (PMID 36293387, 2022). "The downregulated expression of FOXO1 protein in the advanced stages (III and IV) of breast cancer suggests its repressive role in tumor progression and can be considered as the prognostic marker." (PMID 35309123, 2022). "QNPs enhanced the inhibitory role of quercetin in cervical and breast cancer through multiple routes of action, mainly apoptosis induction via PI3K, p-Akt suppression with concomitant caspase, and FoxO1 activation." (PMID 35890222, 2022). "AS1842856 is a targeted inhibitor that can prevent FOXO1 translocation to the nucleus, which blocks Lapateni resistance of MYC-induced breast cancer." (PMID 34123834, 2021). "miR-486-5p has been detected in various cancer cells, and its overexpression inhibits cell proliferation in leukemia cells, through targeting forkhead box protein O1 (FOXO1), and accelerates anti-proliferative effects via PIM-1 in breast cancer cells." (PMID 34830336, 2021). "In breast cancer, GAS5 participates in the activation of proteins that include PTEN, PDCD4, DKK2, FOXO1, and SUFU through a ceRNA mechanism mediated by various miRNAs, including miR-21, miR-222, miR-221-3p, miR-196a-5p, and miR-378a-5p." (PMID 34202777, 2021). "It is upregulated in breast cancer and enhances tumor growth and progression by silencing the protein tyrosine phosphatase, PTPN9 and the tumor suppressor genes FOXO1 and FOXO3a." (PMID 34199293, 2021). "Overexpression of FOXO1 and FOXO3 proteins in breast cancer has been shown to inhibit the growth of breast cancer cells." (PMID 32332845, 2020). "Inhibition of PI3K/Akt pathway by its inhibitors, MK-2066, and GDC0941, revealed the upregulation of FOXO1 and downregulation of MALAT1 in breast cancer cells." (PMID 32708561, 2020). "In our study, we found weak correlations between FOXO1 and FOXO3 RNA and protein expressions in breast cancer." (PMID 32332845, 2020).
breast carcinoma (continued). "Our previous study showed that activation of Akt resulted in the dysregulation of FOXO1, which then led to HER2+ breast cancer cells becoming resistant to trastuzumab." (PMID 32708561, 2020). "Altogether, these results strongly suggest that FOXO1 and FOXO3 proteins act as tumor suppressors in breast cancer." (PMID 32332845, 2020). "In fact, the downregulation of FOXO1 correlates with reduced survival in soft tissue sarcoma, acute myeloid leukemia (AML), and breast cancer." (PMID 32629884, 2020). "Consistently, experimental depletion of Uev1 in breast cancer cells inhibits AKT signaling and promotes FOXO1 and BIM expression to reduce cell survival under serum starvation stress and enhance chemosensitivity." (PMID 31827405, 2019). "Disturbing the TRIB3-AKT interaction suppresses BCSCs by accelerating FOXO1 degradation and reducing SOX2 expression in mouse models of breast cancer." (PMID 31844113, 2019). "Our work indicates that TRIB3 links stress signals to breast cancer stemness through the coordination of FOXO1 and SOX2 in breast cancer with high TRIB3 expression." (PMID 31844113, 2019). "FOXO1 is closely related with CRC progression, and also promotes invasion and metastasis of some subsets in colon and breast cancers." (PMID 31395078, 2019). "The PI3K/AKT/p70S6K signaling pathway, which has been reported to be involved in the nucleus-cytoplasm shuttling of FOXO1, another forkhead protein family member, was previously shown to participate in FOXP1 regulation in breast cancer." (PMID 29848352, 2018). "We found that hsa-miR-21 and has-miR-96 forms the interaction model mostly with oncogenes, but hsa-miR-10b forms three interaction models with tumor suppressors, FOXO1, SERPINB5, and STARD10, to have statistical dependency on breast cancer." (PMID 28793339, 2017). "Previous studies suggest that Cdc25A can increase Foxo1 stability, while Foxo1 can enhance transcription of MMP1, leading to enhanced breast cancer cell metastasis." (PMID 28334049, 2017). "In breast cancer, cell division cycle 25A (CDC25A) mediates metastasis by regulating MMP1 through FOXO1." (PMID 27486383, 2016). "MiR-96 has been reported to exert an oncogenic effect in non-small cell lung cancer, esophageal cancer, breast cancer, hepatocellular carcinoma, and prostate cancer, respectively by inhibiting the expression of FOXO3, RECK, FOXO3a and FOXO1." (PMID 26582573, 2015). "SIRT1 inhibition was reported to reduce both the nuclear FOXO1 levels and MRP2 expression while enhancing cytotoxic effects of paclitaxel and doxorubicin in tamoxifen-resistant breast cancer cells." (PMID 25569080, 2015). "First, the cis-regulatory elements for HSF, TEF-1, and C/EBPα and β were statistically enriched at genomic RU486/PR-targets in uterine leiomyoma, whereas E2F, FOXO1, FOXA1, and FOXF sites were preferentially enriched in breast cancer cells." (PMID 22272226, 2012). "Because BITC-induced autophagy as well as cell growth inhibition is significantly attenuated by knockdown of FoxO1, we conclude that this protein plays a critical role in autophagic cell death by BITC treatment in human breast cancer cells." (PMID 22457718, 2012). "Interestingly, among various cancer cell lines examined, HCT116 cells exhibited the highest mRNA and protein levels of FOXO1, while MDA-MB-231 (breast cancer) and H1299 (lung cancer) cells displayed comparatively lower expression." (PMID 41124013, 2025). "Inhibition of FOXO1 through drugs like AS1842856 and trifluoperazine has shown promise in reducing blood sugar, impairing autophagy in diabetes, preventing left ventricular atrophy, and overcoming chemoresistance in breast cancer." (PMID 39844998, 2025). "In this study, we demonstrated for the first time that overexpression of FOXO1 could reverse the EMT process, leading to the suppression of metastasis in breast cancer." (PMID 39135158, 2024).
breast carcinoma (continued). "Mechanistically, FOXO1-regulated CYP1B1-AS1 affected the heterodimeric enzyme NAE by directly binding to NAE1 to regulate protein neddylation, thereby inhibiting the malignant progression of breast cancer." (PMID 37640964, 2023). "By suppressing FOXO1 degradation and increasing SOX2 transcription, TRIB3 can help breast cancer." (PMID 36245981, 2022). "Thus, our data indicate that GCs induce TTP expression in a FOXO1-dependent manner, and that GC-induced TTP mediates the anti-viability activity of GCs in breast cancer cells." (PMID 36430156, 2022). "Our data indicate that these miRNAs may be involved in FOXO1 and NRAS modulation, breast cancer development, and progression." (PMID 34299605, 2021). "In MDA-MB-435 breast cancer cells, cotreatment of doxorubicin with TSN can significantly enhance the anti-breast cancer activity, and the mechanism may depend on the FoxO1-Bim/Noxa pathway." (PMID 35140606, 2021). "MiR-27 acts as a tumor suppressor in breast cancer, by targeting SPRY1, BAK, FOXO1, and CBLB/GRB2." (PMID 34199293, 2021). "Therapeutic targeting of the PI3K/Akt pathway and nuclear retention of FOXO1 could suppress the upregulation of MALAT1, re-sensitize the sensitivity of trastuzumab, and prevent breast cancer progression." (PMID 32708561, 2020). "Moreover, restoration of FOXO1 activity contributes to a reduction in cancer cells due to a decrease in cell proliferation and induction of apoptosis in MCF-7 breast cancer cells." (PMID 32704044, 2020). "GOLPH3 suppresses the forkhead box O1 (FOXO1) transcription factor via AKT signaling to regulate the expression of cell-cycle inhibitors, thereby contributing to cell proliferation and tumorigenesis in breast cancer." (PMID 33134174, 2020). "Our results strongly suggest that FOXO3 protein, but not FOXO1 protein, acts as a tumor suppressor in breast cancer." (PMID 32332845, 2020). "In breast cancers, SOX2 is up-regulated by the transcription factor FOXO1 (Forkhead box protein O1), the long non-coding RNA SOX2OT (SOX2 overlapping transcript), and the EGFR/Stat3 signaling pathway in a paracrine manner involving tumor-associated macrophages." (PMID 33553286, 2020). "In HER2 positive breast cancer cells AS1842856 restores Lapatinib sensitivity by reducing the FOXO1-mediated MYC upregulation and in ovarian cancer cells AS1842856 prevents the FOXO1-induced senescence by inhibiting the progestin-induced p21 expression." (PMID 31591479, 2020). "Thus, TRIB3 consistently reduced the phosphorylation of AKT1, a kinase that can interact with FOXO1 25, indicating that the AKT-FOXO1 interaction plays a critical role in TRIB3-enhanced breast cancer stemness." (PMID 31844113, 2019). "Similarly, in other cancer types including colorectal cancer, breast cancer and pancreatic cancer cell lines, GSK126 treatment also increased H3K27ac level but decreased H3K27me3 level in the FOXO1 promoter." (PMID 31410199, 2019). "Indeed, tamoxifen-resistant breast cancer cells over-expressed MRP2 that in the promoter region contains four FOXO binding sites, a finding that renders FoxO1 a regulator of MRP2-mediated resistance." (PMID 30646603, 2019). "The PI3K-AKT pathway has been shown to inhibit FOXO1, 3 and 4 expression, suggesting that FOXO6 overexpression in breast cancers could be due to impaired activity of this pathway." (PMID 29484124, 2018). "Overexpression of FOXO1 and FOXO3 has been shown to inhibit the growth of breast cancer cells." (PMID 29484124, 2018).